CD4 (CD4 molecule)
Diseases named in the same sentence as CD4 in open-access papers (continued):
Sharing a sentence is not in itself a finding about the gene and the disease.
non-small cell lung carcinoma (160 papers, 2006 to 2026). A group of at least three distinct histological types of lung cancer, including non-small cell squamous cell carcinoma, adenocarcinoma, and large cell carcinoma. "A higher anti-TERT Th1 response and low expression of PD-1+ T cell immunoglobulin (Ig) mucin-3 (TIM-3)+ CD4+ T exhausted cells are associated with better patient prognosis in non-small cell lung cancer (NSCLC)." (PMID 38328405, 2023). "On the other hand, tumour-associated neutrophils can produce CCL17, recruiting CD4 T regulatory cells that promote immune evasion and cancer development in non-small cell lung cancer." (PMID 35226704, 2022). "Similar to CD8+ TILs, CD20+ TILs were reported to be associated with CD4+ TILs in non-small cell lung cancer." (PMID 33726701, 2021). "Zheng showed that high PD-1 expression on peripheral CD4+ T cells is associated with inferior clinical response in non-small-cell lung carcinoma patients who received anti-PD-L1 treatment." (PMID 34054956, 2021). "Indeed, they are associated with a good prognosis in many cancers such as non-small cell lung cancer (NSCLC) or colorectal cancer (CRC) where the frequency of tumor infiltrating Th1 polarized CD4 T cells is directly linked with a good clinical outcome." (PMID 34064410, 2021). "Here, we delineated CD4+ TRMs in non-small cell lung cancer (NSCLC) using CD103 and CD69 as defining markers and demonstrated that their transcriptional and phenotypic profiles closely resembled those observed in murine models." (PMID 41486351, 2026). "apCAFs with immunostimulatory features have been reported in non-small cell carcinoma (NSCLC) adjacent to CD4+ T cells, suggesting a context-dependent function." (PMID 40940809, 2025). "We analyzed changes in intratumoral CD8+ and CD4+ T-cell subpopulations following neoadjuvant chemoimmunotherapy in non-small cell lung cancer." (PMID 41230345, 2025). "Interactions between follicular helper T cells (CD4 TFH), tissue-resident T cells (CD8 TRM), and B cells mediated by the CXCL13–CXCR5 axis are crucial for anti-tumor immunity in EGFR-mutated non-small cell lung cancer (NSCLC)." (PMID 40406143, 2025). "An investigation in oligometastatic non-small cell lung cancer (NSCLC) has demonstrated significantly elevated peripheral CD4+ T-cell levels in patients with brain metastases compared to healthy controls." (PMID 40895621, 2025). "Human non-small-cell lung cancer cells EVs can efficiently promote the proliferation of CD4+ cells and restrain tumor development." (PMID 38832506, 2024). "In contrast, the group found that this drug increased the number of CD4+CD25+ T cells in patients with non-small-cell lung cancer treated with vinorelbine and cisplatin." (PMID 39519128, 2024). "In a retrospective cohort study of non-small cell lung cancer, high baseline absolute CD4+T lymphocyte count helps extend progression-free survival." (PMID 38179053, 2023). "The elevated circulating CD8+PD-1+/CD4+PD-1+ ratio prior to immunotherapy has also been shown to be correlated with good survival times in advanced non-small cell lung cancer patients treated with anti-PD-(L)1treatment." (PMID 37974194, 2023). "The circulating CD4+ T cells are significantly decreased in non-small cell lung cancer and small lung cancer patients." (PMID 36901716, 2023). "In order to determine if CCR8+ FOXP3− Tconv cells are enriched in human tumors, we analyzed CD4+ T cells from 48 patents with non-small cell lung carcinoma (NSCLC) by flow cytometry." (PMID 38100544, 2023). "Reports suggested that higher level of PD-1+CD3+CD4+ Th cells correlated with better survival in non-small cell lung cancer (NSCLC) patients." (PMID 38102684, 2023). "A CD4 helper T-inducer cancer vaccine (UCPVax), previously studied in non-small cell lung cancer (NSCLC), has been investigated in combination with ICI for HPV+ cancers including SCCA in VolATIL." (PMID 38063578, 2023).
non-small cell lung carcinoma (continued). "The prevalence of Meflin-positive CAFs was positively correlated with CD4-positive T-cell infiltration and vascularization within non-small cell lung cancer tumors." (PMID 35236758, 2022). "Decreased CD4 + TN/TM ratio has also been observed in 76 non-small cell lung cancer (NSCLC) patients compared to 28 age and sex-matched healthy volunteers." (PMID 35858901, 2022). "In a previous study, we demonstrated that CD4+ T cell immunity in the peripheral blood before therapy predicted the antitumor efficacy of second-line nivolumab therapy in patients with non-small cell lung cancer (NSCLC)." (PMID 36528575, 2022). "More recently, CD4+ CD103+ TRM cells infiltrating human non-small cell lung cancer (NSCLC) were shown to produce IFN-γ and TNF-α, resembling a TH1 phenotype." (PMID 36385379, 2022). "miR-142-5p has been identified to regulate CD4+ T cells through PD-L1 expression via regulating the PTEN pathway in non-small-cell lung cancer." (PMID 35251375, 2022). "In a retrospective cohort study of non-small cell lung cancer, a high baseline absolute CD4+ T lymphocyte count contributed to longer progression-free survival." (PMID 36451825, 2022). "A high proportion of activated CD4 memory T cells was found in non-small cell lung cancer and in renal cell carcinoma after radiation therapy." (PMID 35928267, 2022). "A previous study on non-small cell lung cancer (NSCLC) showed that CD4+ Tregs were responsible for accelerated tumor growth." (PMID 35855334, 2022). "High densities of TS-infiltrating CD4+ T cells favored DSS of non-small-cell lung carcinoma patients, whereas their frequency in the tumor islands did not have any effect on DSS." (PMID 35267524, 2022). "A study on RFA combined with surgical resection for non-small cell lung cancer showed intense infiltrations of CD4+ and CD8+ lymphocytes at the perimeter of the RFA-treated tumor tissue." (PMID 33804429, 2021). "Meanwhile, activated CD8 + T cells and high densities of tumor-infiltrating CD4+ Th1 cells indicated prolonged survival in non-small cell lung cancer." (PMID 34699318, 2021). "We conclude and propose that the presence of specific CD4 T cell memory subsets in peripheral blood before the initiation of treatments is a strong predictor of responses in non-small cell lung cancer patients." (PMID 33329566, 2020). "Then, we detected Fas and IL-9 expression in CD4+ T cells from tumor tissues in a cohort of 36 cancer patients with non-small-cell lung carcinoma (NSCLC)." (PMID 31266950, 2019). "Gemcitabine combined with cisplatin chemotherapy significantly reduce the population of CD4 + CD25 + FOXP3+ Treg in patients with non-small cell lung cancer." (PMID 27435207, 2016). "Various studies have demonstrated that tumor-infiltrating lymphocytes, especially CD4+ helper T cells, are present in the lungs of patients with non-small cell lung cancer." (PMID 24872958, 2014). "A high number of stromal CD4+ T cells were found to represent an independent positive prognostic factor in non-small cell lung cancer." (PMID 24860567, 2014). "Notably, previous studies have confirmed that tumor-infiltrating B cells can affect the survival of non-small cell lung cancer patients by regulating the phenotype of CD4 + T cells." (PMID 41003841, 2025). "A previous study identified a new Treg subpopulation, CD13-expressing CD4+CD25high Tregs, among CD4+CD25high Tregs in the peripheral blood of patients with non-small cell lung cancer and found that CD13+ Tregs with high levels of Foxp3 expression exhibited enhanced immunosuppressive functions." (PMID 38822041, 2024). "Interestingly, we observed a relatively higher correlation between the CD4_Pro_MKI67 and CD4_Treg_CTLA4 subsets, which is consistent with their known immunosuppressive roles in non-small cell lung cancer." (PMID 38596689, 2024).
non-small cell lung carcinoma (continued). "Additionally, our previous research proved that CD4+CD25hiCD127low Tregs in peripheral blood had great value for the selection of appropriate individualized treatment options for patients with non-small cell lung cancer." (PMID 37210494, 2023). "In a study of patients with non-small-cell lung cancer, flow cytometry and RNA analysis revealed that the percentage of circulating CD4 + and CD8 + T cells correlated with inflamed tumors, indicating that all of these markers play an important role in the anti-tumor responses." (PMID 35661905, 2023). "KLRB1 (coding for CD161) gene expression shows a positive association with favorable outcome in non-small-cell lung cancer, independently of the size of T and B cell infiltrates, making CD161-expressing CD4+ T cells ideal candidates for anti-tumor recall responses." (PMID 35853971, 2022). "It has been demonstrated that the combined use of tubulin inhibitors and ICIs was successful for the treatment of non-small cell lung cancer, because tubulin inhibitors enhanced CD4 + and CD8+ T cell activity, inhibited Tregs, induced dendritic cell maturation, and increased M1 macrophages." (PMID 35562800, 2022). "To this end, we investigated the associations between APE1 and TILs in non-small cell lung cancer (NSCLC) and explored whether APE1 would influence the associations of CD4+ T cells infiltration with the prognosis of patients." (PMID 33676448, 2021). "In addition, the expression of CD3, CD4 on T cells is known to be a good indicator of overall survival in non-small cell lung cancer patients, and increased CD4/CD8 ratio correlates with tumor grade and stage and overall survival." (PMID 27029063, 2016). "This trial enrolled patients with stage IV non-small cell lung cancer (NSCLC) that were treated with universal cancer peptide-based vaccine (UCPVax) that is based on human telomerase reverse transcriptase (hTERT) derived-MHC class II peptides capable of eliciting CD4+ Th1 responses." (PMID 41282134, 2025). "Study reported that increasing numbers of CD4+ T cells correlated significantly with improved disease-specific survival and that a high density of stromal CD4+ T cells was a favorable independent prognostic factor in non-small cell lung cancer (NSCLC) patients." (PMID 33301062, 2021). "In non-small cell lung cancer, CLEC2D is restricted to germinal center B cells in tertiary lymphoid structures, interacting with CD161+ CD4+ T cells to contribute to better outcomes." (PMID 40938562, 2026). "In a 2022 phase II trial of non-small cell lung cancer (NSCLC) patients, perioperative immunonutrition elevated serum IgG, IgA, IgM, and CD4+ counts while increasing pre-Alb levels." (PMID 41573253, 2025). "The GSE128822 dataset involves gene expression profiles of FACS-sorted Tregs (CD4+CD25+CD127-CCR8+ICOS+ and CD4+CD25+CD127-CCR8-ICOS-) from five surgically resected and cryopreserved human non-small-cell lung cancer carcinomas." (PMID 39273290, 2024). "Links to poor outcomes have been observed for Tregs located near CD8+ T cells in HPV- oral squamous cell carcinoma (OSCC) and in CRCs with microsatellite instability, and for both CD4+ and CD8+ Tregs located near non-small cell lung cancer (NSCLC) cells." (PMID 37936700, 2023). "Immune profiling studies on non-small cell lung cancer (NSCLC), renal cancer and melanoma PDOs demonstrated retention of CD8+ and CD4 + T cells, CD14/CD69+ macrophages, NK and NKT cells and B cells." (PMID 37438470, 2023). "Dendritic cells loaded with HHP tumor cells secrete proinflammatory cytokines and stimulate IFN-γ-producing tumor antigen-specific CD4+ and CD8+ T cells in non-small cell lung cancer." (PMID 37872173, 2023). "To investigate the expression of MEOX1 in more detail, we reanalyzed a recently published single-cell RNA-seq dataset that comprised human CD4+ and CD8+ T cell populations from non-small-cell lung cancer patients." (PMID 37559728, 2023).
non-small cell lung carcinoma (continued). "In mouse models of non-small cell lung carcinoma (NSCLC), depletion of apCAFs led to accelerated tumour growth accompanied by decreased numbers of tumours infiltrating CD4+ and CD8+ T cells." (PMID 36480035, 2023). "CD4 +, CD8 +, and CD4+/CD8 + in the study group were higher than those in the control group, suggesting that single-port thoracoscopic surgery for non-small cell lung cancer can effectively protect cellular immune function." (PMID 35242806, 2022). "We examine the expression of YTHDF1, YTHDF2, CD8, CD4, and FOXP3 to identify their prognostic or predictive role for PD-1/PD-L1 inhibitor in non-small cell lung cancer (NSCLC)." (PMID 36479088, 2022). "Researchers also found that in non-small cell lung cancer, EGFR-mutant and ALK-rearranged tumors responded poorly to anti-PD-1/PD-L1 treatment and exhibited higher infiltrations of CD4+ memory resting T cells." (PMID 36588538, 2022). "Further, PD-L1 expression on T cells has been found to correlate with increased CTC survival in metastatic genitourinary cancer and advanced non-small cell lung cancer (NSCLC), along with lower CD4+ and CD8+ T cell numbers." (PMID 35207611, 2022). "In a mouse non-small-cell lung-cancer model, the inhibition of CDK4/6, the downstream target of p16, resulted in increased CD4 and CD8 T cell infiltration in the tumor." (PMID 34948172, 2021). "A study of 83 late-stage non-small cell lung cancer patients, which employed an antibody-dependent FISH methodology for enumerating CTCs, found that the percentages of CD3+, CD4+ and NK-cells were lower in CTC-positive than in CTC-negative patients." (PMID 34572916, 2021). "In human patients with non-small cell lung cancer (NSCLC), TIM-3 is predominantly expressed in tumor-infiltrating CD4+ and CD8+ T cells, but expressed at minimal levels on T cells from peripheral blood." (PMID 28300768, 2017). "Concurrent infiltration by both CD4+ and CD8+ T cells was reported to represent a favorable prognostic factor in esophageal squamous cell carcinoma and non-small cell lung cancer, suggesting that both cell types cooperate to fight cancer." (PMID 24860567, 2014). "An investigation of 335 cases of non-small cell lung cancer (NSCLC) showed that an increased number of epithelial CD8+, stromal CD8+ and stromal CD4+ lymphocytes was significantly correlated with improved disease-specific survival." (PMID 25202383, 2014). "There was a positive correlation between a high density of CD4+ and CD8+ lymphocytes in stroma and improved disease-specific survival in non-small cell lung cancer." (PMID 21298041, 2011). "Furthermore, as previously discussed, SNORA38B promotes the secretion of IL-10 by tumor cells, which recruit CD4+FOXP3+ regulatory T cells and reduce CD3+CD8+T cell infiltration in the TME of non-small-cell lung cancer." (PMID 41019058, 2025). "For instance, immune profiling studies on non-small cell lung cancer (NSCLC), renal cancer, and melanoma PDOs with TIME have revealed that the CD8+ and CD4+ T cells, CD14/CD68/CD 69+ macrophages, NK (natural killer), NKT (natural killer T) and B cells were well-maintained in tumor PDO models." (PMID 38256166, 2024). "In patients with metastatic melanoma, or non-small cell lung cancer, the in vitro responsiveness of PBMC-derived CD4 T cells to IFN-β was more effective at predicting subsequent response to α-PD1 therapy than was the state of the CD4 T cells directly ex vivo." (PMID 38055623, 2023). "Using a non-small cell lung cancer dataset (n = 153) as a case study, we found that the spatial heterogeneity in the TME cellular composition of CD14+ cells, CD19+ B cells, CD4+ and CD8+ T cells, and CK+ tumor cells, had a significant non-zero effect on the overall survival (p = 0.027)." (PMID 37756338, 2023).
non-small cell lung carcinoma (continued). "Lung club cells have been shown to be crucial for the efficacy of radiation and immune checkpoint inhibitor combined therapy for non-small cell lung cancer, and MHC class II expressing lung epithelial cells act as antigen-presenting cells to direct CD4 + T helper cell functions." (PMID 37150829, 2023). "In particular, CD13+CD4+CD25high Tregs exhibited stronger suppressive function than CD4+CD25high Tregs that did not express CD13 and increased in abundance with tumor stage in non-small cell lung cancer (NSCLC) patients treated with pembrolizumab." (PMID 36359776, 2022). "In patients with non-small cell lung cancer, APE1 expression is correlated with tumor-infiltrating lymphocytes, and low APE1 expression together with CD4+ T cell infiltration is correlated with good prognosis, suggesting that APE1 levels regulate the function of CD4+ T cells." (PMID 35296074, 2022). "In contrast, an meta-analysis found that CD4+ T cells in tumor compartment had no influence on OS, while CD8+ T cells were associated with better prognosis in terms of OS in non-small cell lung cancer patients." (PMID 33859531, 2021). "A previous research also indicated that tumor infiltrating CD4+ T cells, not CD8+ T cells, were associated with favorable prognosis in non-small cell lung cancer." (PMID 33859531, 2021). "FOXP4 is also expressed in CD4+ and CD8+ T cells and appears to contribute to cytokine production and memory T cell responses, and a recent study reported FOXP4 as an important regulator of non-small cell lung cancer cells." (PMID 28521775, 2017). "Another clinical study showed that the ratio of CD3+ and CD4+ cells and the CD4+/CD8+ ratio of non-small cell lung cancer patients increased after administering a Taxus decoction, suggesting that Taxus may boost the immunity of patients, thus prolonging their survival time." (PMID 39508039, 2024). "Studies confirmed that many activated CD4+CD25+ T cells play a crucial role in anti-tumor immune responses and are of beneficial prognostic influence in non-small cell lung carcinoma (NSCLC) patients." (PMID 36304453, 2022). "For instance, naive CD4+ T cells with depletion of acid sphingomyelinase (ASM), which is a phospholipids hydrolase enzyme, possess a greater probability to differentiate into Th1 and Th17 cells which can facilitate anti-tumor immunity in non-small-cell lung cancer." (PMID 35720273, 2022). "The CD4+/CD8+ ratio was higher in the GPR87 high-expression group than the low GPR87 expression group, suggesting that the high-expression group patients were correspondingly poorer for non-small cell lung cancer immunotherapy, consistent with the results of the TIDE algorithm analysis." (PMID 35790819, 2022). "Moreover, a previous study showed that in non-small-cell lung cancer, demethylation of the FOXP3 gene promoter could reduce the activity of DNMTs in Tregs CD4+ lymphocytes and downregulate immune responses in the TME." (PMID 35517856, 2022). "However, the Helios+ subpopulation among CD4+Foxp3+ T cells in peripheral blood did not significantly differ between non-small-cell lung cancer (NSCLC) patients and healthy donors." (PMID 34257746, 2021). "In non-small cell lung carcinoma (NSCLC), female-gender patients produce a stronger anti-tumor immune response than male patients, and they have a higher number of activated dendritic cells, CD4+, CD8+, and effector T cells, memory CD4+ T cells, and B cells." (PMID 37666817, 2023). "Indeed, in clinical study, our analysis of specimens from non-small cell lung carcinoma (NSCLC) showed significant correlations between infiltration of both CD8+ and CD4+ T cells into tumour nest and prognosis." (PMID 19277034, 2009).